IGF1 (insulin like growth factor 1)
Diseases named in the same sentence as IGF1 in open-access papers (continued):
Sharing a sentence is not in itself a finding about the gene and the disease.
osteosarcoma (continued). "This research group has addressed the relationship between serum levels of IGF-1, its binding protein (IGFBP-3), and the clinical behavior and outcome of osteosarcoma in children." (PMID 22587902, 2012). "Within the PPTP/C in vivo models, rhabdomyosarcoma and Wilms tumor models consistently show very high levels of IGF2 expression and low levels of IGF1 expression, while IGF2 expression is lower and more variable for neuroblastoma and osteosarcoma models and is lower still for Ewing sarcoma." (PMID 39510293, 2024). "Moreover, mRNA expression of IGF1 and IGF2 in osteosarcoma cells were increased, while the insulin receptor (INSR) and insulin receptor substrate 1 (IRS1) genes were both downregulated." (PMID 37755271, 2023). "Unlike the previous studies, the expression of miR‐29a in osteosarcoma has been evaluated, indicating that IGF1‐30UTR functions as a competing endogenous RNA in increasing angiogenesis by sponging miR‐29." (PMID 36281584, 2023). "Most of the targeted therapies for osteosarcoma have focused on signaling pathways such as human epidermal growth factor receptor (HEGR2), insulin-like growth factor 1(IGF1), and mammalian target of rapamycin (mTOR), which appear overactive in osteosarcoma tumors." (PMID 37175397, 2023). "The IGF-1 level showed no remarkable different between chemotherapy-received patients with osteosarcoma and Ewing sarcoma compared to their opposite counterparts." (PMID 36713521, 2022). "As reported in the following lines, it is noteworthy that the majority of the studies available in the Literature concerning miRNAs, the GH/IGF1 axis and the IGF system in osteosarcoma are focused on miRNAs that target, both directly or indirectly, the IGF1R both in vivo and in vitro." (PMID 34484116, 2021). "Moreover, IGF-1 and/or IGFBP-5 participate in the estrogen-mediated regulation of PTH action on Saos2 osteosarcoma cell proliferation and collagen I production." (PMID 34069554, 2021). "In addition, expression of the IGF1R, IGF1 and IGF2 was detected in most osteosarcoma cell lines and patient-derived tissues." (PMID 34440844, 2021). "However, the evaluation of other targets within the GH/IGF1 axis and the IGF system would be of paramount importance to clarify the implications of miRNAs in osteosarcoma development and to identify new possible therapeutic targets." (PMID 34484116, 2021). "OncoLAR®, a long-acting somatostatin analog, which reduces IGF1 levels, was well tolerated but lacked clinical response in osteosarcoma patients." (PMID 34440844, 2021). "To determine whether miR-26a suppresses osteosarcoma cell proliferation through targeting IGF-1, we found that IGF-1 overexpression could rescue growth inhibition of miR-26a." (PMID 27468358, 2015). "Over-expression of the IGF-1 axis may account for an as negative prognostic biomarker for patients suffering from primary bone cancers especially osteosarcoma." (PMID 36713521, 2022). "To test if continuous exposure to insulin can favour tumour growth, we studied insulin/IGF1-dependent activation of ERK1/2 and Akt/PKB by Western blotting, inhibition of apoptosis by ELISA, and induction of proliferation by [3H]-thymidine incorporation in Saos-2/B10 osteosarcoma cells." (PMID 28316059, 2017). "In a retrospective study of 37 patients, it was found that circulating levels of IGF-1 and IGFBP-3 were not predictive of the development or clinical characteristics of pediatric osteosarcoma." (PMID 22587902, 2012).
heart failure (81 papers, 2009 to 2025). Inability of the heart to pump blood at an adequate rate to meet tissue metabolic requirements. "This antagonistic theory of aging is supported by other studies and genes, for example the genetic overactivation of insulin-like growth factor (IGF-1) signaling improves cardiac function in young mice but causes premature heart failure during aging." (PMID 39706842, 2024). "Research has shown that levels of serum IGF-1 were decreased in heart failure patients, and lower levels of peripheral IGF-1 were linked to an increased risk of heart failure." (PMID 39355348, 2024). "This study provided a summary of the research conducted on the correlation between IGF-1 and the risk of heart failure." (PMID 39355348, 2024). "For example, healthy participants of the Framingham Heart Study with serum Igf1 levels below the median value have had a risk of developing heart failure twice as high as individuals with Igf1 levels above the median value." (PMID 37541969, 2023). "In fact, Igf1 is known to convey cardioprotective actions and is even demonstrated to allow for a prognostic assessment of heart failure risk." (PMID 37541969, 2023). "Ghrelin promotes GH and IGF-1 functions, inhibits sympathetic activity, activates parasympathetic activity, and improves cardiac function associated with heart failure by regulating energy metabolism." (PMID 36009817, 2022). "There was limited evidence of associations between IGF-1 levels and heart failure, atrial fibrillation and ischaemic stroke." (PMID 32548700, 2020). "There are also data linking low serum IGF-1 levels to an increased risk of CV diseases, including coronary artery and ischemic heart diseases, myocardial infarction, heart failure (HF), and stroke." (PMID 29036907, 2017). "However, other studies reported that the level of IGF-1 declines with age, and its decrease has been associated with age-related disorders such as CVDs and heart failure." (PMID 41050739, 2025). "Furthermore, low levels of IGF-1 are related to congestive heart failure, and receptor deficiency in cardiac muscle even leads to early death from heart failure in mice." (PMID 36009569, 2022). "In contrast, some other cross-sectional and nested case–control studies (including 57–374 cases) reported that elevated IGF-1 levels were associated with lower prevalence or incidence of coronary artery disease, heart failure, atrial fibrillation and ischaemic stroke." (PMID 32548700, 2020). "Heart failure can increase inflammation, cause lower protein synthesis than degradation, reduce mitochondrial function, increase reactive oxygen species (ROS), change hormone content such as angiotensin II (AngII) and insulin like growth factor 1 (IGF-1), thus leading to muscle atrophy." (PMID 33195482, 2020). "Ghrelin emerges as a potential therapy for heart failure by improving mitochondrial function in cardiac tissue, often via GH and insulin-like growth factor-1 (IGF-1) signaling." (PMID 41303478, 2025). "Studies involving patients with pathological cardiac hypertrophy and heart failure have shown elevated levels of angiotensin II (Ang II), endothelin-1 (ET-1), insulin-like growth factor 1 (IGF-1), and catecholamines compared to healthy individuals." (PMID 40943251, 2025). "The detailed characteristics of all the eligible studies for the association with the insulin-like growth factor-1 (IGF-1) levels and heart failure (HF)." (PMID 39355348, 2024). "Initially, our aim is to investigate if there is a connection between heart failure and changes in serum IGF-1 levels." (PMID 39355348, 2024). "Most studies have indicated that peripheral insulin-like growth levels factor-1 (IGF-1) is valuable in diagnosing heart failure, although the results have been inconsistent." (PMID 39355348, 2024). "To help solve the debate, we performed a meta-analysis to explore the relationship between IGF-1 and heart failure (HF)." (PMID 39355348, 2024).
heart failure (continued). "For instance, in a cohort study of 337 patients, IGF-1 was reported as a predictor of cardiovascular mortality in patients with heart failure, so older patients with lower serum IGF-1 levels showed higher mortality." (PMID 37372424, 2023). "In clinical practice, serum IGF-1 levels are decreased in heart failure (HF) patients and serve as a predictor of cardiovascular mortality in this condition." (PMID 36970368, 2023). "In an experimental animal model of heart failure, it was documented that AngII decreased the levels of circulating IGF1 and elevated IGF1 and the expression of its specific receptor in the cardiac muscles." (PMID 35326441, 2022). "Acute injection of IGF-1 into apparently healthy individuals and cardiac failure patients resulted in inotropic effects." (PMID 33905470, 2020). "Other studies confirmed this observation, with the human MGF peptide administration to mice facilitating the actions of the locally produced IGF1 during the progression of heart failure to improve cardiovascular function." (PMID 32977489, 2020). "Clinical studies have shown that the GH/IGF-1 axis is impaired in heart failure with approximately 40% of patients presenting GH or IGF-1 deficiency." (PMID 29137319, 2017). "Oxidativeand hypertrophic stresses contribute to the pathogenesis of heart failure.Insulin-like growth factor-1 (IGF-1) is a peptide hormone with a complexpost-transcriptional regulation, generating distinct isoforms." (PMID 20228935, 2009). "There have already been several attempts targeting IGF1 signaling in clinical trials, but the therapeutic effects in patients with heart failure are controversial.Moreover, uncontrolled activation of the IGF1 pathway may cause tumorigenesis in other organs." (PMID 37149504, 2023). "Furthermore, IGF-1 levels in patients with HFpEF (heart failure with preserved ejection fraction) were significantly higher than the IGF-1 levels of their HFrEF (heart failure with reduced ejection fraction) counterparts." (PMID 37372424, 2023). "The reduction of IGF-1 plasma concentration correlates with an increased risk of heart failure in elderly patients without a previous history of heart disease." (PMID 35721030, 2022). "According to a previous experimental study, IGF-1 inhibits the progression of cardiomyopathic disease in a transgenic mouse model of heart failure, suggesting that heart failure may benefit from early treatment with interventional IGF-1." (PMID 35890161, 2022). "This adds extra value to our study, as interventional irisin increases the expression of the IGF-1 gene, which might protect against heart failure." (PMID 35890161, 2022). "Finally, elevated IGFBP2 inhibits IGF-1, which regulates LV dysfunction and is a biomarker for predicting heart failure." (PMID 33810615, 2021). "There was no strong evidence for associations between IGF-1 levels and heart failure (OR 1.01 [95% CI 0.97, 1.06]), atrial fibrillation (OR 1.03 [95% CI 0.97, 1.08]) or ischaemic stroke (OR 1.03 [95% CI 0.98, 1.08])." (PMID 32548700, 2020). "Finally, a powerful regulatory link was recently shown in the heart between IGF-1 and miR-1 in a mouse model of pressure-overload-induced heart failure." (PMID 30823517, 2019). "IGF-1 is mainly reduced in patients with severe heart failure or cardiac cachexia." (PMID 29137319, 2017). "The propensity to cause hypertrophy without heart failure is also seen with over-expression of insulin-like growth factor 1 (IGF-1) and insulin-like growth factor 1 receptor (IGF1R)." (PMID 22912742, 2012). "Also, after the onset of heart failure, Igf1 has been shown to mediate beneficial effects." (PMID 37541969, 2023). "Additionally, enhanced IGF-1 signaling, such as that occurs as a result of growth hormone (GH) therapy, may be beneficial in heart failure." (PMID 35721030, 2022).
heart failure (continued). "Although IGF-1 and IGFBP-2 are known to be predictors for mortality in patients with heart failure, their use in clinic as prognostic biomarkers for acute coronary syndrome (ACS) requires investigation." (PMID 36970368, 2023). "As the search for a novel and effective therapy to prevent the progression of post-MI heart failure continues, we tested a supramolecular UPyGF-hydrogel loaded with VEGF/IGF1." (PMID 31852978, 2019). "Mir-345-3p however has been recently shown to increase in concentration in early heart failure, attenuates LDL apoptosis induced inflammation and is a known modulator of insulin like growth factor receptor-1 (IGF-1), which is itself a strong potentiator of platelet activation." (PMID 32277149, 2020). "In addition, when used together, IGF-1 and VEGF exerted complementary therapeutic effects in post-infarction heart failure." (PMID 25830234, 2015). "In contrast to mice, enhancing IGF-1 signaling had negative effects on heart failure in rats." (PMID 41050739, 2025). "However, our goal was to clarify transcriptional and posttranscriptional regulation of myostatin/IGF-1 signaling which is missing from the literature and not the recapitulation of other studies mainly concentrating on protein changes in heart failure patients." (PMID 25591711, 2015). "Moreover, it was shown that the concentration of IGF-binding protein (IGFBP)-1 and the ratio of IGFBP-1/IGF-1 in patients with heart failure were significantly lower than in a control group, and they can be used to easily identify patients with and without heart failure." (PMID 37372424, 2023). "The complex relationship between insulin-like growth factor 1 (IGF-1) levels and heart failure (HF) is not fully understood, particularly across different populations and conditions." (PMID 39544311, 2024). "Within the Ly6clow group of macrophages that proliferates 1 week after TAC, on the other hand, it is the CCR2+ macrophages that are affected by the absence of CD8+T cells and that produce the growth factors (IGF-1, AREG, OSM) which are supposed to be involved in reduced heart failure." (PMID 34745139, 2021).
hypopituitarism (80 papers, 2007 to 2026). A condition of diminution or cessation of secretion of one or more hormones from the anterior pituitary gland. "The diagnosis of GHD in adults usually needs GH provocative testing or low IGF-1 concentration with three or more other pituitary hormone deficiencies." (PMID 38318292, 2024). "PitNET can also cause hypopituitarism due to its occupying effect, and the deficiency of pituitary hormones usually begins with the GH/IGF-1 axis." (PMID 38370349, 2024). "In IGF-1 deficiency, anorexia nervosa, aging, and hypopituitarism, serum IGF-1 concentrations are reduced, leading to decreased bone weight or the slowing of growth due to a lack of physiologic effects of IGF-1 on osteoblasts." (PMID 37266131, 2023). "In our experience, 15% of pediatric patients with TBI developed isolated long-term pituitary hormone deficiency, including two with low IGF-1 levels and short stature and one with low TSH levels." (PMID 36843696, 2023). "The other six cases did not have dynamic testing for GH deficiency but had low–normal IGF-1 levels with the presence of three or more pituitary hormone deficiencies to suggest they would have inadequate response to dynamic testing." (PMID 35532784, 2022). "GH provocative tests are required in patients with pituitary tumors, except for those with multiple pituitary hormone deficiencies (≥3 pituitary hormone deficiencies) and low serum IGF-1 levels (< -2.0 standard deviation [SD] score)." (PMID 35452483, 2022). "These patients have in common low insulin-like growth factor 1 (IGF-1) and structural damage at the hypothalamus or pituitary level with childhood onset or acquired during adulthood and/or three or more pituitary hormone deficiencies." (PMID 32309600, 2018). "While it is widely accepted that a low IGF-1 value in the presence of multiple pituitary hormone deficiencies provides strong evidence of GHD in adults, most patients will require provocative testing to confirm the diagnosis." (PMID 22899919, 2012). "In fact, Safb1−/− mutant mice die perinatally and surviving individuals exhibit dwarfism due to low levels of insulin-like growth factor 1, a phenotype compatible with hypopituitarism, i.e., isolated growth hormone deficiency." (PMID 17931718, 2008). "They identified acquired prolactin deficiency in 22 out of 369 patients with hypopituitarism and demonstrated an independent association between prolactin deficiency and lower serum insulin-like growth factor-1 (IGF-1) levels in severe growth hormone (GH) deficiency patients." (PMID 39037546, 2024). "Although IGF-1 can be helpful in identifying GHD in individuals with established hypopituitarism, its sensitivity is limited in diagnosing isolated GHD." (PMID 40641631, 2025). "Mutant Prop-1 results in pituitary hormone deficiency that induces a secondary deficiency in insulin-like growth factor 1 (IGF-1), as hepatic IGF-1 synthesis is almost exclusively triggered by GH action." (PMID 40140153, 2025). "This relationship is in agreement with what was observed in hypopituitary adults in whom IGF-1 levels reflected hypopituitarism severity." (PMID 39997750, 2025). "Minimum yearly measurements of IGF1, PRL, cortisol, DHEAS, LH, FSH, testosterone or estradiol, FT4, and TSH are needed in brain-irradiated children since they are at risk to develop hypopituitarism over time." (PMID 39415786, 2024). "Additional examinations detected hypopituitarism with low IGF‐1 level (81 ng/ml, normal range 95–460)." (PMID 36398453, 2023). "Growth failure screening suggested hypopituitarism with central hypothyroidism and low IGF1 at baseline, however, dynamic tests confirmed normal axis." (PMID 37386483, 2023). "Age, sex, body mass index, tumor size, invasiveness, prolactin staining, ki-67 index, and GH/IGF-1 levels were significantly correlated with preoperative hypopituitarism and hyperprolactinemia." (PMID 35154007, 2021).